STAT3 (signal transducer and activator of transcription 3)
Diseases named in the same sentence as STAT3 in open-access papers (continued):
Sharing a sentence is not in itself a finding about the gene and the disease.
amenorrhea (1 paper, 2025). The absence of menses in a woman who has achieved reproductive age. "This study highlights significant associations between PFAS exposure, particularly PFHxS and n_PFOA, and long-term amenorrhea, with serum globulin and STAT3 serving as mediators in the underlying mechanisms." (PMID 40137514, 2025). "The dysregulation of STAT3 is also associated with metabolic disorders, chronic inflammation, and hormonal imbalances, which may profoundly impact the mechanisms of long-term amenorrhea." (PMID 40137514, 2025). "Future research should focus on validating these findings in diverse populations and deeply exploring the molecular mechanisms underlying the interactions between PFASs, serum globulin, and STAT3 signaling in the pathogenesis of long-term amenorrhea." (PMID 40137514, 2025). "Dysregulation of the STAT3 pathway alters hormonal balance, contributing to the development of amenorrhea." (PMID 40137514, 2025). "Given the evidence that PFAS exposure may alter immune and endocrine functions, along with our findings regarding globulin as a mediator, this suggests a potential link between STAT3 and serum globulin as mediators in the occurrence of long-term amenorrhea." (PMID 40137514, 2025).
anal tumor (1 paper, 2017). "Lysates of anal tumors from tumor-bearing mice showed significantly higher expression of p-STAT3 compared to perianal skins from wild type (WT) mice." (PMID 28747781, 2017). "p-STAT3 was upregulated in both cancer cells and infiltrating immune cells shown in immunohistochemical staining of perianal skin and anal tumor." (PMID 28747781, 2017).
androgenetic alopecia (1 paper, 2025). "A study of CCCA specimens revealed increased numbers of perifollicular lymphocytes with phosphorylated STAT3 compared to androgenetic alopecia controls." (PMID 40778340, 2025).
anthracosis (1 paper, 2013). A chronic lung disorder characterized by deposition of coal dust in the lung parenchyma leading to the formation of black nodules and emphysema. "CD68+ myeloid clusters associated with anthracosis and with an immunosuppressive and metastasis-promoting phenotype and elevated overall STAT3 activity were observed in uninvolved lymph nodes." (PMID 23717691, 2013). "STAT3 activation in anthracotic myeloid clusters also associated with anthracosis intensity." (PMID 23717691, 2013).
aortic atherosclerosis (1 paper, 2008). A atherosclerosis that involves the aorta. "Our findings furnish a new mechanism through which pravastatin can prevent aortic atherosclerosis via attenuating IL-6 action by the modulation of STAT3 activity in apoE-/- mice." (PMID 19330073, 2008). "Our results suggested that pravastatin’s aortic atherosclerosis preventing action via attenuation of IL-6 action may partially depend on modulation of STAT3 activity." (PMID 19330073, 2008). "The purpose of this study was to determine whether pravastatin’s prevention of aortic atherosclerosis via attenuation of IL-6 action depends on modulation of STAT3 activity." (PMID 19330073, 2008). "However, the relationship between pravastatin preventing aortic atherosclerosis and modulating STAT3 remains elusive." (PMID 19330073, 2008).
Atherosclerotic lesion (1 paper, 2021). A lesion associated with atherosclerosis, a multifactorial and multipart progressive disease manifested by the focal development within the arterial wall of lesions, that ranges from the development of a fatty streak, plaque progression, and plaque disruption. "In addition to the high expression of IL-6, an inducer of STAT3 in atherosclerotic plaques, activation of STAT3 was also detected in plaques, and was associated with the progression of atherosclerotic lesions." (PMID 34504432, 2021).
autoimmune type 1 diabetes (1 paper, 2022). Autoimmune disease wherein the body's own immune system attacks and destroys the cells within the pancreas that produce insulin. "Increased STAT3 (Tyr705) phosphorylation after IL-6 stimulation was recently described in patients with autoimmune type 1 diabetes, and this increased responsiveness was seen both for CD4+ and CD8+ T cells." (PMID 35566660, 2022).
autosomal dominant polycystic kidney disease (1 paper, 2022). Autosomal dominant form of polycystic kidney disease. "Given that Smyd2 could methylate and activate the transcription factor STAT3 in autosomal dominant polycystic kidney disease and adipogenesis is intimately linked to STAT3, we were curious whether Smyd2 regulates adipocyte differentiation via activation of STAT3." (PMID 36270984, 2022). "Moreover, Smyd2 regulates autosomal dominant polycystic kidney disease by methylation and activation of STAT3 and p65." (PMID 36270984, 2022).
avascular necrosis (1 paper, 2022). Necrotic changes in the bone tissue due to interruption of blood supply. "This study detected five target genes (IL-1β, STAT3, CAT, PTGS2, and HMOX1) to further study the effects of quercetin, luteolin, kaempferol, cryptotanshinone, and naringenin on the expression of related genes in steroid-induced avascular necrosis of the femoral head." (PMID 35915795, 2022).
bacteremia (1 paper, 2023). "The resulting increase of STAT3 signaling enhances an unexpected PCT production in monocytes in COVID-19 infection not linked to concomitant bacteremia." (PMID 37834815, 2023).
basophilic leukemia (1 paper, 2013). "Interestingly, monomeric IgE induces STAT3 phosphorylation in murine bone marrow-derived mast cells and rat basophilic leukemia cells, and induce the transcription of genes important in cell survival." (PMID 24499258, 2013).
Behavioral Disorders (1 paper, 2025). "Taken together, these results suggest that the JAK2/STAT3 signaling pathway may act as a downstream target in response to a miR‐204‐5p deficiency, thereby contributing to the neuronal injury and behavioral disorders observed in these rats." (PMID 39792918, 2025). "In specific, we show that a miR‐204‐5p deficiency contributes to the enhancement of neuroinflammation and apoptosis involved with the pathogenesis of behavioral disorders via activating its downstream target, the JAK2/STAT3 signaling pathway, which then promotes neuronal deterioration in rats." (PMID 39792918, 2025).
benign breast tumor (1 paper, 2023). "Existing studies have confirmed that the IL-6/JAK/STAT3 signaling pathway is crucial for the proliferation and survival of tumor cells; however, it is unclear whether this pathway plays a similar role in GLM formation and whether its mechanism is similar to that in benign breast tumor." (PMID 37817809, 2023).
benign soft tissue tumors (1 paper, 2011). "STAT3 was found to be overexpressed in malignant tumors, when compared with intermediate and benign soft tissue tumors." (PMID 21575192, 2011).
Bloom syndrome (1 paper, 2023). Bloom syndrome (BSyn) is a rare chromosomal breakage syndrome characterized by a marked genetic instability associated with pre- and postnatal growth retardation, facial sun-sensitive telangiectatic erythema, increased susceptibility to infections, and predisposition to cancer. "Gastroesophageal reflux is mentioned in DGS, Bloom syndrome, and STAT3‐HIES." (PMID 37102642, 2023).
bone marrow cancer (1 paper, 2022). "Over phosphorylation of STAT3 in the JAK/STAT3 pathway due to elevated neuropoietic cytokine activity in mice has been found to promote a metastatic effect in bone marrow cancer." (PMID 35682652, 2022).
bone marrow disease (1 paper, 2016). "In fact, this signaling route is so relevant in tumorigenesis where targeting STAT3 in neoplastic bone marrow disease practically interrupted the progression of metastasis." (PMID 27190500, 2016).
bone marrow failure (1 paper, 2025). "Carriers showed atypical features otherwise tied to the cryptic IEI, such as earlier onset, lower lymphocyte counts, lower STAT3 mutational rate, and higher proportions of hypogammaglobulinemia and immune cytopenia/bone marrow failure than noncarriers." (PMID 40309770, 2025).
bone metabolism disorders (1 paper, 2021). "Hence, we proposed STAT3 to be a suitable pharmacological target for the treatment of AD-HIES-like skeletal defects and other bone metabolism disorders through regulating bone homeostasis." (PMID 34824272, 2021).
bowel obstruction (1 paper, 2021). "VNS improves inflammation and post-operative bowel obstruction in the POI model by activating STAT3 pathways in intestinal macrophages, both of which are anti-inflammatory by the α7-nAChR-mediated Jak2-Stat3 signaling pathway." (PMID 34335306, 2021).
bronchiolitis obliterans syndrome (1 paper, 2021). A lung disorder that is mainly associated with chronic allograft dysfunction after lung transplantation and that is characterized by inflammation and fibrosis of bronchiolar walls that reduce the diameter of the bronchioles and result in progressive and irreversible airflow obstruction. "However, miR-21-5p inhibition in cultures of bronchiolitis obliterans syndrome (BOS) derived myofibroblasts did not significantly affect STAT3 mRNA and protein expression levels." (PMID 33804639, 2021).
bronchogenic carcinoma (1 paper, 2022). A lung carcinoma arising from the bronchial epithelium. "The constitutional activation of STAT3 has been observed in bronchogenic carcinoma by researchers." (PMID 36118847, 2022).
C. perfringens infection (1 paper, 2023). "As for day 19, C. perfringens infection significantly increased STAT3 expression, but the SOCS1 expression was also raised." (PMID 38136901, 2023).
calcification (1 paper, 2022). Process by which organic tissue becomes hardened by the physiologic deposit of calcium salts. "It was also suggested that this suppressive effect was induced by the Janus kinase 2 (JAK2)/signal transducer and activator of transcription 3 (STAT3) pathway, and that adiponectin may have an important role in the treatment of vascular calcification." (PMID 36289903, 2022).
campomelic dysplasia (1 paper, 2017). "Comparison of phenotypic abnormalities in Stat3 loss-of-function mice relative to Sox9 haploinsufficient mice and patients with campomelic dysplasia." (PMID 28166224, 2017).
cardiac arrest (1 paper, 2016). Cessation of breathing and/or cardiac function. "In this study, we found that urocortin treatment can activate key pro-survival signal transducers including Akt, ERK and STAT-3 after cardiac arrest and resuscitation." (PMID 27832152, 2016). "STAT-3 was phosphorylated and activated at tyrosine 705 and serine 727 after cardiac arrest." (PMID 27832152, 2016).
cardiac sarcoidosis (1 paper, 2021). Sarcoidosis affecting the tissues of the heart. "The myocardial accumulation of monocyte/macrophage-derived OSM, along with the expression of Reg3A and Reg3γ in remodeling cardiomyocytes, emphasizes the prevalence of an OSM/OSMR/Stat3/Reg axis in the development of cardiac sarcoidosis." (PMID 33923774, 2021).
cardiac tumor (1 paper, 2015). "The clear positive correlation between STAT3 activation and cardiac lesions indicates that STAT3 activation is causative for cardiac tumor development in this model." (PMID 25528766, 2015).
carotid atherosclerosis (1 paper, 2025). A thickening and loss of elasticity of the walls of carotid arteries that occur with formation of atherosclerotic plaques. "This study further elucidates the mechanism by which the inflammatory factor CXCL16 and the STAT3/NF-κB pathway participate in the inflammatory response in carotid atherosclerosis." (PMID 40165931, 2025). "Moreover, a positive feedback loop exists between CXCL16 and inflammatory factors such as IL-17A and TGF-β, mutually promoting their expression and accelerating carotid atherosclerosis progression via activation of the STAT3 and NF-κB pathways." (PMID 40165931, 2025).
cat-scratch disease (1 paper, 2025). Cat scratch disease is an infectious illness caused by the bacteria bartonella (Bartonella henselae). "Bartonella hensalae, which causes cat scratch disease in humans, employs the effector BepD to activate STAT3 in a c-Abl kinase-dependent mechanism to suppress tumor necrosis factor-α signaling and stimulate IL-10 production." (PMID 40188438, 2025).
chickenpox (1 paper, 2015). A contagious childhood disorder caused by the varicella zoster virus. "STAT3 activation was shown to be critical for replication of VZV that causes varicella (chickenpox) during primary infection and zoster (shingles) upon reactivation." (PMID 26199948, 2015).
cholangitis (1 paper, 2023). An acute or chronic inflammatory process affecting the biliary tract. "Unfortunately, we could not directly study the relationship between STAT3 phosphorylation and PSC disease progression because clinical events such as death, transplantation, CCA, and recurrent cholangitis were infrequent in our patients." (PMID 37256725, 2023).
Cholestatic liver disease (1 paper, 2017). "We have recently shown that the cytokine IL-6 and the cytokine-inducible transcription factor STAT3 protect from cholestatic liver injury and fibrosis in the Mdr2−/− mouse model for cholestatic liver disease." (PMID 27568040, 2017). "Our data demonstrate hepatoprotective functions of the STAT3-EGFR signaling axis in cholestatic liver disease." (PMID 27568040, 2017). "Hepatoprotective functions of STAT3 signaling in cholestatic liver disease have been investigated in mice lacking STAT3, IL-6, gp130, or express pathway specific gp130 mutants." (PMID 27568040, 2017).
chronic bronchitis (1 paper, 2026). A type of chronic obstructive pulmonary disease characterized by chronic inflammation in the bronchial tree that results in edema, mucus production, obstruction, and reduced airflow to and from the lung alveoli. "The study highlights the role of JAK/STAT signalling in COPD, with STAT3 linked to neutrophilic inflammation and STAT6 to eosinophilic inflammation and chronic bronchitis." (PMID 41846690, 2026).
chronic nasopharyngitis (1 paper, 2023). "A research discovery unveiled the expression pattern of JAK/STAT3 in both NPC and chronic nasopharyngitis." (PMID 37932756, 2023). "Notably, the JAK/STAT3 signalling exhibited markedly elevated levels in NPC (60.2% and 70.9%), contrasting with the figures observed in chronic nasopharyngitis (12.8% and 14.1%)." (PMID 37932756, 2023).
colon adenoma (1 paper, 2025). An adenoma that arises from the colon. "Taken together, the transcriptomic results indicate that there is a marked anti-oncogenic effect of TTI-101 on the CRC transcriptome mediated largely by its targeting of STAT3 and STAT1 in the colons of TTI-101-treated AOM-DSS mice, which helps to explain its ability to reduce colon adenomas." (PMID 41226842, 2025).
colon diseases (1 paper, 2025). "Phosphorylation modification is the final form of STAT3 activation, which mainly includes tyrosine and serine phosphorylation sites.STAT3 phosphorylation is involved in the occurrence and development of various colon diseases and also plays an important role in UC." (PMID 39773987, 2025).
colorectal polyps (1 paper, 2024). "AG inhibited colitis-associated colon carcinogenesis in mice via preventing colon shortening and reducing the number of colorectal polyps though inhibiting STAT3." (PMID 38783955, 2024).
Constipation (1 paper, 2022). Infrequent or difficult evacuation of feces. "Furthermore, the network pharmacology analysis showed that Akt1, Stat3, Mapk8, Hsp90aa1, Cat, Alb, Icam1, Sod2, and Gsk3b can be regarded as the core anti-constipation targets." (PMID 35408632, 2022).
COPA syndrome (1 paper, 2020). "Some newly reported etiologies such as STING–associated vasculopathy with onset in infancy, COPA syndrome and STAT3 mutation were included in PID associated ILD." (PMID 31969166, 2020).
demyelination (1 paper, 2021). "Interestingly, dampening astrocyte reactivity (i.e., via STAT3 pathway inactivation) increases the number of OPC-derived Schwann cells in rodent demyelination lesions." (PMID 34381334, 2021).
dentine dysplasia (1 paper, 2026). "Furthermore, we generated conditional knockout mice targeting Stat3 in Osterix-expressing odontoblast progenitors, which consequently exhibited significant dentine dysplasia." (PMID 41985508, 2026).
dermatofibrosarcoma protuberans (1 paper, 2021). Dermatofibrosarcoma protuberans (DFSP) is a rare infiltrating soft tissue sarcoma, generally of low grade malignancy, arising from the dermis of the skin and characteristically associated with a specific chromosomal translocation t(17;22). "In a clinicopathological analysis, STAT3, ERK, and PD-L1 are associated with the progression of dermatofibrosarcoma protuberans." (PMID 34503167, 2021).
Dn (1 paper, 2011). "Overexpression of Nrdp1 decreased the phosphorylation of Akt, ERK/12, and STAT3, and the decreased kinase activity was reversed with Dn-Nrdp1 infection in cardiomyocytes." (PMID 21738612, 2011).
Down syndrome (1 paper, 2025). "The biomarkers most frequently analyzed in studies of Down syndrome were IL-10, TNF-alpha, IL-1 beta, IL-4, IFN-gamma, and the genes STAT1, STAT3, and SOCS3, all of which are involved in the regulation of the immune response and periodontal inflammation." (PMID 41462866, 2025).
dry-mouth (1 paper, 2025). "Quercetin mitigates salivary gland cell apoptosis and inflammation by inhibiting the LP/OB-R/JAK2/STAT3 signaling pathway, thereby providing new opportunities for alleviating dry-mouth symptoms in SS." (PMID 41255601, 2025).
duodenal adenocarcinoma (1 paper, 2025). A carcinoma that arises from glandular epithelial cells of the duodenum. "The HIF1α, STAT3, and MYC expression levels in duodenal adenocarcinoma were analyzed alongside their correlation with Linc01559." (PMID 40722682, 2025).
Ehrlich tumor (1 paper, 2022). "Consistent with those, our data showed excessive activation of STAT3, demonstrated by STAT3 phosphorylation, in response to elevated IL-6 plasma concentration in Ehrlich tumor-bearing mice compared to controls." (PMID 35847939, 2022).
Enterococcus faecalis infection (1 paper, 2025). A bacterial infection induced by Enterococcus faecalis which is the most prevalent species (along with Enterococcus faecium) cultured from humans, accounting for more than 90% of clinical isolates. "In two types of mouse periapical inflammation models, pulp cavity exposure and Enterococcus faecalis infection, p-STAT3 was positively correlated with the number of osteoclasts." (PMID 40016707, 2025).
erectile dysfunction (1 paper, 2025). Persistent or recurrent inability to achieve or to maintain an erection during sexual activity. "In the context of erectile dysfunction (ED), STAT3 may act by affecting vascular endothelial function and smooth muscle cell proliferation and apoptosis." (PMID 40443781, 2025).
follicular thyroid cancer (1 paper, 2017). "Furthermore, OB3 reduced phosphorylation of STAT3 in follicular thyroid cancer cells." (PMID 28750624, 2017).
frontotemporal dementia (1 paper, 2025). Frontotemporal dementia (FTD) comprises a group of neurodegenerative disorders, characterized by progressive changes in behavior, executive dysfunction and language impairment, as a result of degeneration of the medial prefrontal and frontoinsular cortices. "Overexpression of STAT3 improves LTP and spine density in the hippocampus in a mouse model of frontotemporal dementia." (PMID 41428145, 2025).
Fulminant hepatic failure (1 paper, 2020). Hepatic failure refers to the inability of the liver to perform its normal synthetic and metabolic functions, which can result in coagulopathy and alteration in the mental status of a previously healthy individual. "The effects on molecular signaling pathways of AMPK, mTOR, P65, and STAT3 are also consistent with the previous researches, in which Plumbagin protects liver against fulminant hepatic failure and chronic liver fibrosis in LX-2 cells." (PMID 33456673, 2020).